VDR (vitamin D receptor)
Diseases named in the same sentence as VDR in open-access papers (continued):
Sharing a sentence is not in itself a finding about the gene and the disease.
asthma (continued). "Thus, we recommend further examination of the interaction between ICS use and VDR activity, as Vitamin D supplementation is widely recommended in asthma." (PMID 33799333, 2021). "The mRNA expression of VDR was only slightly increased in polyI:C-stimulated BSMCs and this effect was significantly increased by the addition of 1,25D3 (0.866 ± 0.23-fold increase, p = 0.01 in asthma and 1.6 ± 0.73-fold increase in COPD, p < 0.05)." (PMID 34512638, 2021). "The CC genotype of the VDR rs2228570 and the GG genotype of VDBP rs7041 were observed to be significantly increased in patients compared to controls and this increase associated with asthma development." (PMID 31541492, 2020). "The role of the VDR locus in the development of asthma and allergy is still under investigation." (PMID 26346690, 2015). "Furthermore, both VDR and CYP2R1 polymorphisms have been reported to be correlated with susceptibility to other allergic diseases, such as asthma." (PMID 26177022, 2015). "In this study, we tested whether polymorphisms of genes encoding for vitamin D receptor (VDR), vitamin D 25-hydroxylase (CYP2R1) and vitamin D binding protein (GC) were associated with asthma in the Chinese Han population." (PMID 21810276, 2011). "We have not found associations between that exonic variants in the VDR and CYP2R1genes and asthma or asthma-related traits in our Chinese population." (PMID 21810276, 2011). "The hypothesis that the vitamin D pathway plays a role in autoimmune diseases such as asthma, originates from the identification of VDR in immunological relevant cells, including antigen-presenting cells and activated T lymphocytes." (PMID 19852851, 2009). "The hypothesis that VDR plays a role in asthma was also reinforced by the resistance of VDR knock-out mice to experimentally induced asthma." (PMID 19852851, 2009). "Taken together, these studies clearly support VDR as a possible candidate gene for asthma." (PMID 19852851, 2009). "Variants in CYP2R1, CYP27B1 and CYP24A1 or other genes in the metabolic pathway of vitamin D have not been tested so far with asthma or allergy but several of the VDR-controlled genes tested here already have been associated with asthma and allergy." (PMID 16600026, 2006). "As these effects are primarily mediated through the vitamin D receptor (VDR), single base variants in this gene may be risk factors for asthma or allergy." (PMID 15651992, 2005). "Although asthma is the complex disease with the largest number of genome scans (currently more than 15 studies), few genes have been associated with the disease (as far as we know; those are ADAM33, DPP10, PHF11, GPRA, and Vitamin D receptor)." (PMID 16115313, 2005). "Specifically, genetic alterations in two critical loci - the vitamin D receptor (VDR) gene and the group-specific component (GC) gene encoding vitamin D-binding protein (VDBP) - have been identified as potential contributors to increase susceptibility to asthma." (PMID 40936925, 2025). "There is a possibility that vitamin D and VDR may regulate immune markers that promote asthma." (PMID 37407930, 2023). "However, we observed that VDR rs2228570 is not a risk factor for asthma development in allele level (OR = 1.67, 95% CI = 0.89 to 3.14, P = .11)." (PMID 31541492, 2020). "It has been shown that variations in VDR gene may impact on progression of asthma." (PMID 31541492, 2020). "However, cell transfer and bone marrow transplantation showed that VDR KO T cells could induce asthma in the WT host and therefore VDR expression in the lung might account for the increased resistance of the VDR KO mice to allergic asthma." (PMID 25912039, 2015). "Allergies and asthma could be the result of unbalanced metabolic transformation or inadequate vitamin D receptor (VDR) binding, leading to plasma accumulation of active/inactive vitamin D metabolites, predominance of pro-inflammatory cytokines and an impaired immuno-modulation." (PMID 21494627, 2011).
asthma (continued). "In this study we set out to evaluate whether the variants of genes encoding for the key components of vitamin D pathway, including CYP2R1, VDR, and DBP, were associated with asthma or asthma-related phenotypes in a case-control design study in the Chinese Han population." (PMID 21810276, 2011). "This may also increase the probability of VDR to be a candidate gene for asthma." (PMID 19622139, 2009). "None of these SNPs were associated with asthma, leaving VDR as the most likely causal gene." (PMID 19852851, 2009). "Another research among a German population has also tested the same hypothesis, however, there was no preferential transmission of VDR variants to children with asthma." (PMID 19622139, 2009). "Although a preferential transmission of vitamin D receptor variants to children with asthma could not be confirmed, it raises the possibility of a protective effect in unaffected children." (PMID 15651992, 2005). "A preferential transmission of vitamin D receptor variants to children with asthma could not be confirmed but raises the possibility of a protective effect in unaffected children." (PMID 15651992, 2005). "A preferential transmission of vitamin D receptor variants to children with asthma could not be confirmed but raises the possibility of a protective effect for unaffected children." (PMID 15651992, 2005). "Moreover, the interaction between genes and environmental factors such as sun exposure, diet, or interactions of VDR gene with other genes involved in vitamin D metabolism in asthma and atopy may play an additional role, especially in complex diseases such as asthma." (PMID 37407930, 2023). "In the present study, for the first time we examined the Vit D pathway molecules included serum Vit D and vitamin D‐binding protein (VDBP) and also genetic variations in the vitamin D receptor (VDR) and VDBP in a Kurdish population with asthma." (PMID 31541492, 2020). "We also evaluated the frequency of VDR rs1544410, rs2228570, and VDBP rs7041 SNPs and the progressive role of these variations in asthma patients." (PMID 31541492, 2020). "Although misclassification in defining the disease status is more likely in epidemiological definitions of asthma, we do not think that this could have been influenced by the type of VDR genetic variants of the subjects and thus confound the recovered associations." (PMID 26346690, 2015). "We sequenced all 8 exons of VDR and all 5 exons of CYP2R1 in a Chinese case-control cohort of asthma consisting of 467 cases and 288 unrelated healthy controls." (PMID 21810276, 2011). "Discrepancies between studies on VDR, VDBP gene SNP in atopy or asthma may be obtained due to different study populations with geographical and ethnical differences among the subjects involved in these studies." (PMID 37407930, 2023). "On top of that, study of Kurdish population showed increased level of serum VDBP in asthmatic patients compared to the control group and revealed that variations in VDR and VDBP gene may impact on progression of asthma." (PMID 37407930, 2023). "The rs59128934 is located in an intronic region on the VDR gene, however, it is thought that this SNV might decrease vitamin D levels, which could lead to asthma." (PMID 34343413, 2021). "Interestingly, we observed a higher grade of VDR and TLR3 activation in BSMCs from subjects with asthma and COPD when compared with controls." (PMID 34512638, 2021). "Besides, we found that VDR rs2228570 and VDBP rs7041 correlated to asthma exacerbation and should be considered as potential genetic factors in asthma progression in the Kurdish population." (PMID 31541492, 2020). "Further understanding of the molecular mechanisms by which 1,25D3, CYP11A1 and VDR interact to regulate the plasticity and/or stable conversion of CD8+ T cells may provide new targets and novel therapeutic strategies in asthma." (PMID 26750596, 2016).
asthma (continued). "(Albeit, more genetic work is necessary to clarify this since vitamin D receptor knockout mice do not develop the murine model for asthma)." (PMID 19519921, 2009). "SNPs in 5 genes showed a p-value < 0.05 with asthma (IL10, IL12B, VDR, CARD15 and CYP24A1)." (PMID 16600026, 2006). "While asthma involved pathways like NFAT in regulation of the immune response and other lymphocyte activation pathways including signaling through IL-4, IL-8, IL-3 and IL-9 in CD8+ cells, the most prominent pathway in CD4+ cells was VDR/RXR activation signaling." (PMID 32900903, 2020).
cardiac hypertrophy (60 papers, 2010 to 2025). "Cardiomyocyte-specific VDR deletion causes cardiac hypertrophy, whereas 1,25(OH)2D partially suppresses it in neonates." (PMID 39812046, 2025). "In experimental and clinical studies, respectively, VDR knockdown or vitamin D deficiency is associated with remarkable cardiac hypertrophy, activation of the renin angiotensin system, cardiac dysfunction, and failure." (PMID 35726330, 2022). "The VDR is abundantly expressed in the heart with global VDR ablation reported to cause cardiac hypertrophy under normal resting conditions." (PMID 30273386, 2018). "The results of animal studies demonstrated myocardial hypertrophy and dysfunction with a hypercontractile state in both conditions of vitamin D deficiency as well as in VDR knockout models." (PMID 29865146, 2018). "Moreover, the cardiac manifestations in VDR-deficient mice extend to significant myocardial hypertrophy, quantitatively demonstrated by elevated heart weight-to-body weight ratios and augmented expression profiles of natriuretic peptides." (PMID 40880413, 2025). "Consequently, VDR deficiency increases the expression of renin and, therefore, the production of angiotensin II, which can result in hypertension and cardiac hypertrophy." (PMID 36678205, 2023). "In VDR knockout mice, renin and angiotensin II are increased, leading to hypertension and cardiac hypertrophy." (PMID 39812046, 2025). "Finally, transverse aortic constriction (TAC) was performed in adult wild-type mice, double Fgf23/VDR (fibroblast growth factor-23/vitamin D receptor) mutants, and VDR-deficient mice to investigate bone changes in an HF model caused by afterload-induced cardiac hypertrophy, 4 and 6 weeks after TAC." (PMID 41515999, 2025). "In the heart, the presence of the VDR has been demonstrated in cardiomyocytes close to T tubuli as well as in fibroblasts, and cardiac hypertrophy leads to an upregulation of VDR expression at the mRNA and protein levels." (PMID 38892126, 2024). "In VDR-KO mice, cardiac hypertrophy has been observed, whereas VitD treatment improved cardiomyocyte relaxation and, therefore, coronary perfusion during diastole in rodents." (PMID 36678205, 2023). "Global VDR-knockout mice have been reported to have higher BP and to develop cardiac hypertrophy due to increased renin expression and subsequent RAAS activation." (PMID 36364874, 2022). "Experimental studies conducted on VDR-knockout mice highlighted a dramatic increase in cardiovascular dysfunction in affected animals that developed ventricular hypertrophy, heart failure, hypertension, and upregulation of RAAS." (PMID 36012412, 2022). "Some investigations suggest the importance of vitamin D/VDR system in controlling cardiac hypertrophy, a dominant feature of several heart disease, and diastolic function." (PMID 34944459, 2021). "Systemic VDR disruption results in RAAS overstimulation, with a concomitant increase in renin and AngII in the kidneys that indirectly causes cardiac hypertrophy." (PMID 34360540, 2021). "I.e., cardiomyocyte-specific VDR deleted mice (VDRKO mice) and VDR-deleted rats exhibit ventricular hypertrophy, increased matrix turnover and kinetics alteration." (PMID 34944459, 2021). "VDR is expressed in rat and human heart tissue and has a potential role as a modulator of cardiac hypertrophy and failure." (PMID 32911795, 2020). "In a model of VDR null mice, a specific phenotype due to immature muscle-specific genes developed and cardiomyocyte-specific VDR knockout induced cardiac hypertrophy and failure." (PMID 32911795, 2020). "Cardiomyocyte-specific deletion of the vitamin D receptor gene resulted in cardiac hypertrophy and increased left ventricle (LV) weight." (PMID 29865146, 2018). "A later study showed profound heart hypertrophy in vitamin D receptor knockout (VDR-KO) mice, which suggested direct blunting of cardiomyocyte hypertrophy by calcitriol." (PMID 29977597, 2018).
cardiac hypertrophy (continued). "The role of vitamin D in cardiac hypertrophy was shown in studies on VDR knockout mice and 25(OH)D-1-α-hydroxylase knockout mice, which displayed myocardial hypertrophy." (PMID 29849001, 2018). "Cardiomyocyte-specific deletion of the VDR also results in cardiac hypertrophy, and treatment of neonatal cardiomyocytes with 1,25(OH)2D is partially able to suppress hypertrophy." (PMID 28912809, 2017). "Treatment of VDR knockout mice with the ACE inhibitor captopril reduces cardiac hypertrophy and normalizes atrial natriuretic peptide expression." (PMID 28912809, 2017). "A lead compound (known as VDR 4-1) demonstrated potent transcriptional activities in a VDR reporter gene assay, and significantly ameliorated cardiac hypertrophy in cell culture studies and in animal models." (PMID 28814738, 2017). "Targeted ablation of 1-alpha-hydroxylase or VDR or increased β-catenin signaling leads to cardiac hypertrophy." (PMID 27768599, 2016). "The important role of the VDR in mediating the effect of vitamin D has been demonstrated in VDR-knockout mice, in which cardiomyocytes developed cardiac hypertrophy in the face of this depletion." (PMID 25815722, 2015). "Cardiac hypertrophy has been observed in the hearts of VDR-knockout mice, suggesting that vitamin D may affect the myocardium directly and play a role in the development of myocyte hypertrophy." (PMID 38722953, 2024). "Surprisingly, however, normotensive VDR knockout mice also developed cardiac hypertrophy, which could imply that VitD acts directly on cardiomyocytes." (PMID 36678205, 2023). "Thus, we aimed to assess the cardioprotective potential of paricalcitol, a vitamin D receptor-activator, against cardiac hypertrophy and failure in high-fat high-fructose-fed rats." (PMID 35726330, 2022). "In a seminal study published in 2002, Li and coworkers reported that mice with a global VDR deletion were characterized by increased blood pressure, cardiac hypertrophy, increased renin mRNA and protein levels, as well as elevated plasma angiotensin II production." (PMID 36501215, 2022). "Moreover, it has been observed that vitamin D receptor knockout mice developed hypertension and cardiac hypertrophy as a result of renin-angiotensin system dysregulation." (PMID 29865146, 2018). "Furthermore, VDR 4-1 therapy significantly suppressed cardiac hypertrophy and progression to heart failure in both vitamin D deficient and normal mice without inducing significant hypercalcemia." (PMID 28814738, 2017). "In addition, supraphysiologic doses of both VDR 4-1 and 1,25-D3 significantly decreased the expression level of biological markers for cardiac hypertrophy, such as Anf, Bnp and β-Mhc mRNA, compared to their vehicle treated littermate." (PMID 28814738, 2017). "However, supraphysiologic dose (3.0 μg/kg) of VDR 4-1 and 1,25-D3 significantly attenuated cardiac hypertrophy with significant improvement of cardiac function compared to the TAC vehicle animals." (PMID 28814738, 2017). "From these data, we conclude that both 1,25-D3 and VDR 4-1 could prevent cardiac hypertrophy with “rescue” concentration of vitamin D in vivo." (PMID 28814738, 2017). "This assumption is supported by experimental data demonstrating that overall deletion and cardiomyocyte-specific deletion of the vitamin D receptor results in cardiac hypertrophy, whereas treatment of neonatal cardiomyocytes with 1,25(OH)2D can partially suppress cardiac hypertrophy." (PMID 27788150, 2016). "In contrast to wild-type and VDRΔ/Δ mutant mice, rFGF23 treatment of 3-month-old Kl−/−/VDRΔ/Δ double mutant mice did not result in renal Na+ retention and heart hypertrophy, showing that the effects of FGF23 on Na+ homeostasis and heart hypertrophy are Klotho dependent, but VDR independent." (PMID 24797667, 2014). "Treatment with captopril reduced cardiac hypertrophy in VDR-knockout mice." (PMID 23800102, 2013).